MALT1 (MALT1 paracaspase)
Diseases named in the same sentence as MALT1 in open-access papers (continued):
Sharing a sentence is not in itself a finding about the gene and the disease.
autoimmune disease (24 papers, 2011 to 2025). A disorder resulting from loss of function or tissue destruction of an organ or multiple organs, arising from humoral or cellular immune responses of the individual to their own tissue constituents. "MALT1-deficient mice have been shown to be protected from autoimmune diseases, such as experimental allergic encephalitis." (PMID 32870913, 2020). "This early differentiation of Tregs requires the proteolytic activity of MALT1, as knock-in mice that only express protease-inactive MALT1 are also Treg deficient and develop an autoimmune disease that is rescued by the transfer of wild-type Treg cells." (PMID 31138793, 2019). "Since aberrant TH-17 responses underlie the pathology of atopic dermatitis and various autoimmune diseases, Malt1 is a rational therapeutic target to attenuate anomalous adaptive immune responses." (PMID 21283787, 2011). "Since MALT1 could reflect disease risk and activity of several autoimmune diseases, it’s interesting to explore whether it could serve as a biomarker for disease monitoring." (PMID 35967391, 2022). "Explanations for this could be that MALT1 enhances NF‐κB signaling, whose activation is correlated with elevated inflammatory status in autoimmune diseases like AS; correspondingly, MALT1 overexpression is linked with enhanced inflammatory status in AS patients." (PMID 35622982, 2022). "Recently, several clinical studies have displayed an increase in MALT1 in autoimmune disease patients." (PMID 38578002, 2024). "MALT1, as a scaffold protein, plays a fundamental role in immunity and inflammation, which is responsible for the occurrence of various autoimmune diseases." (PMID 38578002, 2024). "The relationship of MALT1 with clinical features in several autoimmune diseases has been revealed by previous studies." (PMID 38578002, 2024). "Telmisartan can also be used in COVID-19 treatment, and Risperidal can be used for MALT1-driven cancer or autoimmune diseases." (PMID 34276383, 2021). "Actually, MALT1 KO and PD mice have been shown to be protected from experimental allergic encephalitis but only PD mice exhibited autoimmune disease due to the role of MALT1 enzymatic activity during Treg development." (PMID 32870913, 2020). "We believe that the increased risk for fungal infections has to be subject to clinical monitoring and has to be weighed against possible MALT1 inhibition treatment benefits in patients suffering from autoimmune disease." (PMID 32870913, 2020). "Based on the central role of MALT1 in lymphocyte activation, MALT1 has been identified as a target for therapeutic immunomodulation in chronic inflammatory or autoimmune diseases." (PMID 32870913, 2020). "Together, our data demonstrate that the effects of allosteric inhibition of MALT1 differ from those seen in mice with proteolytically inactive MALT1, and thus we believe that MALT1 is a viable target for B and T-cell driven autoimmune diseases." (PMID 32870913, 2020). "We therefore propose that not the reduced number of Treg per se, but rather impaired Treg functionality is responsible for autoimmune disease development in Malt1-PDT mice." (PMID 31474984, 2019). "Autoimmune disease in Malt1-PD mice was previously explained by a disrupted balance between effector CD4+ T cells and the number of Tregs." (PMID 31474984, 2019). "The anti-inflammatory role of many of the known protease substrates coupled with the critical role for MALT1 in pro-inflammatory signaling has sparked an interest in targeting MALT1 protease activity as a therapeutic strategy for autoimmune diseases." (PMID 29881386, 2018). "Unfortunately, the analysis of other models of autoimmune diseases in MALT1-PD mice has been severely hampered by the fact that these mice spontaneously develop a severe form of autoimmune disease." (PMID 26507244, 2016).
autoimmune disease (continued). "Altogether, these data indicate that small molecule inhibitors of MALT1 not only hold great promise for the treatment of B cell lymphomas but also for autoimmune disorders such as MS." (PMID 25043939, 2014). "Our studies now demonstrate the efficacy of MALT1 protease targeting in the treatment of autoimmune disease." (PMID 25043939, 2014). "The reversible mode of action and effectiveness of MALT1 inhibition by mepazine in vivo indicates a possible clinical use also for the treatment of severe autoimmune diseases." (PMID 25043939, 2014). "Mucosa‐associated lymphoid tissue lymphoma translocation protein 1, which is also known as para‐caspase, is reported to be dysregulated in a series of autoimmune diseases: One research finds that MALT1 is abnormally elevated in ulcerative colitis and Crohn's disease patients." (PMID 35622982, 2022). "Besides, a preceding study investigates the correlation between MALT1 expression and clinical features in autoimmune diseases: MALT1 is positively related to CRP, TNF‐α, and IL‐17A in inflammatory bowel disease patients." (PMID 35622982, 2022). "Therefore, the therapeutic potential of MALT1 inhibition in autoimmune disease and cancer has raised a lot of interest and led to the development of potent small compound MALT1 inhibitors." (PMID 33083726, 2020). "Thus, we consider pharmacological inhibition of MALT1 as a viable target for autoimmune disease mediated by antigens driven activation of Th1/Th17 effector cells and B-cells." (PMID 32870913, 2020). "While this view is supported by several preclinical studies using MALT1 PD animals or tool MALT1 inhibitors, the spontaneous multi-organ autoimmune disease that develops in MALT1 PD animals has raised concerns about the safety of pharmacological inhibition of the MALT1 protease." (PMID 32425939, 2020). "In addition to a decrease in Tregs, also a decrease in the amount of Bregs was suggested to contribute to the autoimmune disease phenotype in Malt1-PD mice." (PMID 31474984, 2019). "However, recent studies showing that Malt1 protease-dead knock-in (Malt1-PD) mice suffer from autoimmune disease have somewhat tempered the initial enthusiasm." (PMID 31474984, 2019). "Interestingly, MALT1 inactivation protected the mice against experimental autoimmune encephalomyelitis (EAE) and colitis, suggesting a critical role for MALT1 in the control of autoimmune diseases." (PMID 30474008, 2018). "Therefore, less potent Malt1 protease inhibition as achieved with mepazine, or less selective Malt1 inhibition may prove to be better strategies to preserve Treg homeostasis in autoimmune diseases and after SOT." (PMID 33042160, 2020). "Consequently, inhibition of MALT1 proteolytic activity has been proposed as an interesting therapeutic approach for autoimmune diseases and certain cancers, which is further supported by promising results with MALT1 protease inhibitors in preclinical mouse models." (PMID 31632405, 2019). "Even though more effective MALT1 inhibitors may be available in the future, the previous clinical use may facilitate a repurposing of mepazine and foster the translation of our findings to the treatment of severe autoimmune diseases in the clinic." (PMID 25043939, 2014). "Most importantly, the therapeutic effect of mepazine in mouse models of autoimmune disease and ABC-type DLBCL has strengthened the belief in therapeutic targeting of MALT1." (PMID 30513612, 2018). "Inhibitors of MALT1 protease, which dampen canonical NF-κB activity without completely blocking it, may be a more attractive option and have recently yielded promising results for treatment of B cell lymphoma and autoimmune disease." (PMID 29472930, 2018).
Immunodeficiency (24 papers, 2015 to 2025). Failure of the immune system to protect the body adequately from infection, due to the absence or insufficiency of some component process or substance. "While complete MALT1 ablation leads to immune deficiency, selective destruction of either scaffolding or protease function provokes autoimmune inflammation." (PMID 38863711, 2024). "MALT1 has an intrinsic T-cell role in regulating homeostasis; patients with homozygous missense variants in MALT1 have severely impaired T-cell proliferation in response to antigens and antibodies, resulting in a combined immunodeficiency." (PMID 38896123, 2024). "Previous investigations have demonstrated that individuals with combined immunodeficiency attributed to MALT1 deficiency present with diminished bone mineral density, leading to the occurrence of several low-impact fractures." (PMID 37251077, 2023). "In fact, TRAF6 and MALT1 paracaspase double mutations yield a reciprocal rescue of both autoimmune phenotypes, resulting in an immunodeficiency as described for global or T-cell specific MALT1-deficient mice." (PMID 36761777, 2023). "Deregulated MALT1 activity has been associated with immunodeficiency, autoimmunity, and cancer in mice and humans." (PMID 31632405, 2019). "The impaired cellular responses and the associated immunodeficiency phenotype of the MALT1-PI mice results thus principally from the inactivation of the proteolytic activity of MALT1." (PMID 30214442, 2018). "Patients with inactivating MALT1 mutations develop immunodeficiency or immune dysregulation, polyendocrinopathy, enteropathy, and X-linked (IPEX)-like syndrome." (PMID 30214442, 2018). "To date, a limited number of MALT1 deficient patients have been described (18, –, 20), each presenting with severe combined immunodeficiency and being highly susceptible to fungal, bacterial, and viral infections." (PMID 29367251, 2018). "A limited number of patients carrying MALT1 mutations leading to severe immunodeficiency have been reported (18, –, 20), further illustrating the key role of MALT1 in innate and adaptive immunity." (PMID 29367251, 2018). "Our nonconsanguineous patient with early onset profound combined immunodeficiency and immune dysregulation due to compound heterozygous MALT1 mutations extends the clinical and immunologic phenotype reported in 2 prior families." (PMID 25627829, 2015). "Dominant-negative mutations causing loss of function in Caspase Recruitment Domain Family Member 11 (CARD11) and biallelic variants in mucosa-associated lymphoid tissue lymphoma translocation protein 1 (MALT1) can lead to combined immune deficiency and atopic disorders, mainly severe AD." (PMID 39962262, 2025). "Thus, complete loss of TRAF6 or selective inactivation of MALT1 catalytic function in mice skews the immune system towards autoimmune inflammation, but distinct mechanisms are responsible for these immune disorders." (PMID 36761777, 2023). "In humans, loss of function mutations in MALT1 generally result in reduced MALT1 protein levels and cause an inborn immunodeficiency that combines increased sensitivity to all types of infections with an IPEX-like syndrome, which is fatal unless treated with hematopoietic stem cell transplantation." (PMID 32425939, 2020). "Finally, we will highlight how dysregulation of MALT1 function can cause pathologies such as immunodeficiency, autoimmunity, psoriasis, and cancer." (PMID 30214442, 2018). "Recent reports of patients with MALT1 missense mutations demonstrated that disruption of MALT1 function has far-reaching consequences for innate and adaptive immunity resulting in combined immunodeficiency." (PMID 27092298, 2016). "Homozygous mutations in MALT1 have been associated with immunodeficiency." (PMID 26569114, 2015). "Furthermore, aberrant expression of MALT1 is linked with immunodeficiency." (PMID 34997981, 2022).
Immunodeficiency (continued). "Malt1 KO mice have simultaneous severe defects in conventional T (Tconv) and regulatory T (Treg) cells, resulting in a net outcome of immunodeficiency." (PMID 36761777, 2023). "Clearly, only the combined mutation of MALT1 scaffolding and protease functions renders conventional T cells inactive, which results in immunodeficiency as observed in T cell-specific Malt1 KO mice." (PMID 36761777, 2023). "Mice expressing a catalytically inactive mutant of MALT1 [C472A knock-in mice, subsequently called MALT1-protease inactive (PI) mice] recapitulate these aspects of the immunodeficiency phenotype of the MALT1 knockout mice to a large extent." (PMID 30214442, 2018). "Moving beyond infections, both MALT1- and BCL10-deficient patients presented simultaneously with immunodeficiency and immune dysregulation, where in addition to recurrent infections, they also developed inflammatory gastrointestinal disease." (PMID 30283440, 2018). "In view of the fact that IBD patients are usually along with immunodeficiency; consequently, MALT1 may be dysregulated in IBD patients." (PMID 34997981, 2022). "The loss of function mutations in the MALT1 gene identified in patients with immunodeficiencies have been associated with high risk of infections, but not with autoimmune conditions." (PMID 32870913, 2020).
Autoimmunity (23 papers, 2014 to 2024). The occurrence of an immune reaction against the organism's own cells or tissues. "The genetic disruption of MALT1 protease activity in Malt1 PD-T mice causes autoimmunity in a T cell intrinsic manner." (PMID 36761777, 2023). "As a counterexample, long-term treatment of psychiatric patients with chlorpromazine, another MALT1 inhibitor, is associated with the induction of autoimmunity markers and occasionally results in a lupus-like disease." (PMID 31474984, 2019). "Genetically engineered mice expressing catalytically inactive MALT1, still exerting its scaffold function, were previously shown to spontaneously develop autoimmunity due to a decrease in Tregs associated with increased effector T cell activation." (PMID 31632405, 2019). "Deregulated MALT1 activity has been associated with autoimmunity and cancer, implicating MALT1 as a new therapeutic target." (PMID 29367251, 2018). "MALT1 is an intracellular protein involved in innate and adaptive immunity and is an interesting therapeutic target because MALT1-deregulated activity has been associated with autoimmunity and cancers." (PMID 29367251, 2018). "Thus, in order to provide evidence that loss of TRAF6 induces autoimmunity through cell-intrinsic MALT1 protease activation, we generated mice in which TRAF6 deletion and MALT1 protease inactivation are combined specifically in T cells." (PMID 36761777, 2023). "However, recent studies showed that MALT1 protease activity is also critical for maintaining Treg function, implicating a risk for autoimmunity when MALT1 protease activity is only lost in adulthood." (PMID 33083726, 2020). "Based on our results, we propose that future risk assessments of MALT1 protease inhibition related to autoimmunity could focus on the effect of MALT1 inhibitors on Treg differentiation, maintenance and functionality." (PMID 31474984, 2019). "The compromised Treg function in MALT1-deficient or -mutant humans and mice raises the concern that prolonged treatment of individuals with MALT1 inhibitors may favor the development of autoimmunity." (PMID 26507244, 2016). "Interestingly, while mice with MALT1-deficient Tregs and mice with enzymatically-dead MALT1 in Tregs both developed autoimmune-like wasting disease, only full MALT1-KO in Tregs reduced splenic Treg frequencies and increased IFNg/IL17 production in conventional CD4 T cells." (PMID 32870913, 2020). "Our case also highlights how MALT1 mutations may lead to immune dysregulation and autoimmunity." (PMID 25627829, 2015). "Here we demonstrate that ablation of TRAF6 in T cells induces autoimmunity via T cell-intrinsic activation of MALT1 substrate cleavage." (PMID 36761777, 2023). "Vice versa, TRAF6 is essential for autoimmunity upon MALT1 protease inactivation in T cells, emphasizing the critical interdependency of MALT1 and TRAF6 to balance T cell activation and homeostasis." (PMID 36761777, 2023). "As a consequence, MALT1 remains a compelling target for the treatment of autoimmunity and inflammation." (PMID 35615349, 2022). "MALT1 PD mice develop serious autoimmunity with inflammation and lymphocyte infiltration in multiple organs, suggesting the role of MALT1 protease activity in immune homeostasis." (PMID 35467421, 2022). "Genetic disruption or short-term pharmacological inhibition of MALT1 protease is effective in several preclinical models of autoimmunity and B cell malignancies." (PMID 32425939, 2020). "The protease MALT1 is a key regulator of NF-κB signaling and a novel therapeutic target in autoimmunity and cancer." (PMID 33083726, 2020). "MALT1 proteolytic activity plays a key role in both immune cells and non-immune cells, and mice expressing a catalytically inactive MALT1 mutant (Malt1-PD mice) were previously shown to suffer from severe autoimmunity." (PMID 31474984, 2019).